MARCKS (myristoylated alanine rich protein kinase C substrate)
Diseases named in the same sentence as MARCKS in open-access papers (continued):
Sharing a sentence is not in itself a finding about the gene and the disease.
cancer (continued). "Both MARCKS and MARCKSL1 are activated by phosphorylation, suggesting that MARCKS-targeted therapies could be used to treat cancer metastasis." (PMID 36230850, 2022). "In addition, MARCKS also has an effect on the sensitivity of cancer cells to chemotherapy drugs and targeted radiation therapy." (PMID 35401213, 2022). "In addition, MARCKS facilitates cancer metastasis through modulating cancer cell migration and invasion." (PMID 36230850, 2022). "How then is MARCKS modulating cancer development and progression?" (PMID 33754052, 2021). "Additionally, while MARCKS exists as a valuable candidate for anti-cancer therapies, currently our grasp on the strategies available to target the gene or protein is still evolving." (PMID 33958003, 2021). "Such inhibition of cancer stemness by MPS peptide may be attributed to the suppression of smoke-induced MARCKS phosphorylation." (PMID 33754052, 2021). "Consequently, a deeper investigation is essential for us to better understand the role of MARCKS in normal and cancer physiology." (PMID 33958003, 2021). "Despite the wealth of evidence of the functionality of MARCKS in various cancers, it is unknown if MARCKS' contribution to cancer progression can be activated by cigarette smoke." (PMID 33754052, 2021). "Indeed, the importance of small non-coding RNA-based inhibition of genetic targets such as MARCKS has been recognized by several studies for its vital therapeutic consequence in multiple cancers." (PMID 33958003, 2021). "Interestingly, the phosphorylated form of MARCKS has been shown to promote cell motility and membrane protrusions and significantly affect the invasiveness of several cancer cells." (PMID 32033033, 2020). "Notably, cancer cells isolated from bone marrow of patients exhibit increased miR23b and decreased MARCKS expression in comparison to cancer cells isolated from the primary breast tumor, suggestive a mechanism specific to the bone metastatic phenotype." (PMID 29642534, 2018). "However, MARCKS has also been found in cell secretome of cancer cells, therefore we cannot exclude a biological role for circulating MARCKS56." (PMID 30420710, 2018). "In vitro models showed that phospho-MARCKS promoted cancer growth and erlotinib resistance." (PMID 28009981, 2017). "Knockdown of MARCKS in cancer cells resulted in decreased adhesion, migration and invasion." (PMID 28765579, 2017). "Stromal MARCKS overexpression in tumors might contribute to cancer-associated fibroblasts activation and to the poor prognosis of EOC, suggesting a potential therapeutic interest of MARCKS inhibition for targeting the cooperative tumor stroma." (PMID 29295532, 2017). "A single study of MARCKS expression in EOC has shown that MARCKS is highly expressed in the ovarian stroma, is required for the differentiation and tumor-promoting function of cancer-associated fibroblasts (CAFs) and is associated with poor survival." (PMID 29295532, 2017). "Several studies in other types of cancers have shown involvement of MARCKS tumor expression in cancer progression, chemoresistance, and suggested that MARCKS inhibition could be a novel therapeutic approach." (PMID 29295532, 2017). "Moreover, MARCKS has been reported to be associated with the PI3K/AKT pathway, which is supposed to be a classical regulator of malignant behaviors in various cancer cells." (PMID 27081703, 2016). "Studies are ongoing to determine what the function of MARCKS is in the nucleus and how it might impact cancer cell biology." (PMID 26470026, 2015). "Another group of differentially expressed proteins are associated with increased cancer cell motility and invasiveness, which include EphA2, BCAS1, S100 protein family members, Rho family members, Ral-A, Rab family members, Cdc42, MARCKS, Ezrin, Galectins 1 and 3 among others." (PMID 22417809, 2012). "Moreover, over-expression of MARCKS in cancer cells results in decreased proliferation while knockdown has been shown to increase migration." (PMID 20957176, 2010).
cancer (continued). "However, whether MARCKS modulates cancer cell migration and invasion in UCEC to impact radiosensitivity requires further investigation." (PMID 39926275, 2025). "These taken together suggests that MARCKS may be cooperating with or promoting NF-κB signaling, leading to more pronounced cancer aggressiveness as demonstrated by the poor outcomes in patients with upregulated NF-κB molecular signatures and increased phospho-MARCKS levels." (PMID 33754052, 2021). "Hence, MARCKS appears to be a phosphorylation-controlled negative regulator of signaling pathways that is dysregulated in cancer, which could be exploited for the design of appropriate drugs targeting MARCKS." (PMID 31058089, 2019). "In experimental models, MARCKS overexpression was shown to suppress cellular senescence and boost the activation of AKT/TWIST1 (Protein kinase B/Twist-related protein 1) signaling to sustain the cancer-associated fibroblasts features, thus supporting tumor cells growth and invasion." (PMID 29295532, 2017). "It is evident that most of them are highly expressed in cancer, with ANXA5, SERPINE1, MARCKS, and MATN3 being particularly significant in their expression levels." (PMID 38287304, 2024). "Based on risk factors, drug sensitivity screening, and the degree of differential expression between cancer and normal tissues, we have identified ANXA5, MARCKS, and SERPINE1 as candidates warranting further research." (PMID 38287304, 2024). "A growing body of evidence implicates the myristoylated alanine-rich C-kinase substrate (MARCKS), and the highly homologous MARCKS-like protein 1 (MARCKSL1) in cancer migration and metastasis." (PMID 36230850, 2022). "Beyond its putative involvement in cancer pathogenesis, LINC01268 (also known as lnc-MARCKS or ROCKI) acts as a master regulator of inflammatory response in macrophages, inducing pro-inflammatory cytokines and chemokines by acting in cis on MARCKS promoter." (PMID 34638230, 2021). "Myristoylated alanine-rich C kinase substrate (MARCKS), a main substrate of protein kinase C (PKC), plays an essential role in cancer development and progression." (PMID 29757215, 2018). "Thus, MARCKS could be an interesting biomarker and target for cancer metastasis." (PMID 29069765, 2017). "Secondly, we plated fluorescently labeled OC cells onto feeder layers of control or MARCKS-silenced MRC5-CAFs and found a notably higher number of cancer cells in co-cultures with control CAFs than in the MARCKS-repressed group." (PMID 27081703, 2016). "MARCKS immunoreactivity was also detected in inflammatory cells and fibroblasts surrounding the carcinoma cells, where HER2 expression was absent." (PMID 40940979, 2025). "In addition, multiplex immunofluorescence would be suitable for assessing the co-expression of MARCKS and EMT proteins on cancer cells." (PMID 36139501, 2022). "MARCKS function depends on its NMD and PSD or ED, which are required for its membrane localization and phosphorylation; therefore, peptides targeting these domains have been developed to inhibit its function in various cancers." (PMID 36230850, 2022). "It is well established that phosphorylation of MARCKS, and not MARCKS expression levels, drives cancer cell proliferation and motility." (PMID 36230850, 2022). "While MARCKS regulates a plethora of processes that impact the oncogenic potential across several cell types, the role of MARCKS as a cancer promoter or a tumor suppressor is still not clearly ascertained." (PMID 33958003, 2021). "Inhibition of MARCKS phosphorylation is capable of trapping NKAP and inactivating NF-kB signaling, leading to suppression of proinflammatory cytokines as well as attenuation of cancer cell aggressiveness and stemness." (PMID 33754052, 2021). "Consequently, peptide inhibition of MARCKS has not been tested for preventing the metastatic spread of cancer, including drug-resistant cancer." (PMID 36551563, 2022).
cancer (continued). "Similarly, unphosphorylated, membrane bound MARCKS or MARCKSL1 have been shown to promote lamellipodium formation, axon outgrowth and cell motility in neurons and cancer cells in some studies, whereas phosphorylated, cytosolic MARCKS has been shown to promote cell motility in other studies." (PMID 29788979, 2018). "MARCKS stromal overexpression was more frequent in IBC than in non-IBC, which could sustain more cancer-associated fibroblasts activation in IBC and higher metastatic potential." (PMID 29295532, 2017). "However, it is not clear that inhibition of MARCKS could circumvent therapeutic resistance in all cancers." (PMID 36230850, 2022). "Additionally, cancers that are driven primarily by the unphosphorylated form of MARCKS may not find a significant role of PKC inhibitors." (PMID 33958003, 2021).
tumor (47 papers, 2009 to 2026). "In this study, we comprehensively screened key genes involved in both fibroblasts and tumor cells, identifying MARCKS proteins as potential diagnostic markers for UTUC." (PMID 38903524, 2024). "The results showed that the CM-miR-143 lipoplexes significantly improved the survival of the mouse model by suppressing pelvic CRC tumor growth; the underlying mechanism partially involves MARCKS downregulation." (PMID 38213952, 2023). "In conclusion, MARCKS promotes migration and invasion and is associated with biochemical recurrence in localised prostate cancer tumours." (PMID 29069765, 2017). "Our previous work has also found that exosomal miR-143-3p might upregulate MARCKS in tumor-associated macrophages and was associated with immune infiltration." (PMID 35432524, 2022). "ex., typical tumor drivers BCAN, APOE, and EGFR or genes associated to neuronal function like EGR1, FOS, and MARCKS)." (PMID 40188875, 2026). "Our findings suggest that MARCKS expression correlates with ER negativity, implicating its potential role in aggressive tumor biology and serving as a potential prognostic indicator." (PMID 40940979, 2025). "In HER2 positive patients, our TCGA analysis confirmed that high MARCKS expression was significantly associated with HER2 positivity, ER and PR negativity, higher tumor mutational burden, and younger age at diagnosis." (PMID 40940979, 2025). "MARCKS and MARCKSL1 are closely linked to tumor development, and part of the mechanism that has been clarified is immune-related, mainly in its widespread presence in innate immune cells and its involvement in the regulation of immune function." (PMID 37340044, 2023). "The situation is further complicated by contradictory reports regarding the role of phosphorylated versus an unphosphorylated form of MARCKS as an oncogene versus tumor suppressor in blood cancers." (PMID 33958003, 2021). "Vice versa our data suggest the prevention of MARCKS inhibition by reversing hyperphosphorylation or genomic restoration after deletion as two promising approaches to overcome tumor cell resistance towards chemotherapeutic ABCB1 substrates." (PMID 32056006, 2020). "Disinhibition of MARCKS function via bosutinib led to increased sensitivity of tumor cells towards chemotherapy, suggesting a therapeutic benefit of bosutinib treatment in CRC chemotherapy." (PMID 32056006, 2020). "Using HT-29 cells as a model for MARCKS hyperphosphorylation, we present herein evidence that the tyrosine kinase inhibitor bosutinib can restore MARCKS function in a tumor context." (PMID 32056006, 2020). "For instance, we found the microtubule-interacting protein stathmin (STMN1) and myristoylated alanine-rich protein kinase C substrate (MARCS) to be increased at the tumor periphery in most of the analyzed specimens." (PMID 29363612, 2018). "Regarding the stroma staining and using the same positivity cut-off (1% of stained stromal cells), 77% of tumor samples showed positive MARCKS immunostaining versus 22% of normal samples (p = 1.41 × 10−9; Fisher’s exact test)." (PMID 29295532, 2017). "By contrast, stromal MARCKS expression was more frequent in tumor samples (77%) than in normal samples (22%; p = 1.41 × 10−9)." (PMID 29295532, 2017). "Seventy-five percent of normal samples showed positive epithelial MARCKS staining versus 50% of tumor samples (p = 6.02 × 10−3)." (PMID 29295532, 2017). "MARCKS protein expression was then measured on the 118 tumor samples and 40 normal samples present on the tissue-microarray (TMA)." (PMID 29295532, 2017). "Tumor samples showed heterogeneity with respect to MARCKS staining: 18% were scored as MARCKS-positive (stained cells ≥ 1%) and 82% as MARCKS-negative." (PMID 28009981, 2017). "We have here analyzed MARCKS protein expression in stromal and epithelial cells in tumor samples of patients with EOC treated at Salah Azaiez Institute of Tunis, Tunisia, and searched for correlations with clinicopathological features and survival." (PMID 29295532, 2017).
tumor (continued). "Using 1% of stained tumor cells as positivity cut-off, 89 samples (18%) exhibited a positive MARCKS expression (≥ 1% of stained cells), whereas 413 (82%) were MARCKS-negative." (PMID 28009981, 2017). "We have shown that MARCKS tumor expression is more frequent in stromal cells than in epithelial cells, and that stromal MARCKS expression is associated with shorter overall survival (OS)." (PMID 29295532, 2017). "A more indirect way is to analyze gene expression profiles of clinical tumor samples according to MARCKS protein expression." (PMID 28009981, 2017). "In contrast, MARCKS level was reduced in the tumor epithelial cells compared with normal ovary epithelial." (PMID 29295532, 2017). "From in silico analyses of public transcriptional data, the authors first showed that, compared with its expression in the tumor epithelial compartment, MARCKS was specifically expressed in the stromal compartment." (PMID 29295532, 2017). "Using 1% of stained epithelial cells as positivity cut-off, we found that 75% of normal samples showed positive MARCKS immunostaining versus 50% of tumor samples (p = 6.02 × 10−3; Fisher’s exact test)." (PMID 29295532, 2017). "In contrast, MARCKS level was reduced in the tumor epithelial cells compared with normal ovary epithelial tissues." (PMID 27081703, 2016). "MARCKS was selected for further study due to its reported role in regulating tumor cell adhesion and migration; its impact on CAFs activity has not been well studied." (PMID 27081703, 2016). "Here, we determined that myristoylated alanine-rich C-kinase substrate (MARCKS) was highly expressed in ovarian stroma, and was required for the differentiation and tumor promoting function of CAFs." (PMID 27081703, 2016). "We found that MARCKS expression was elevated in tumor stroma and reduced in tumor epithelia as OC progresses, and was increased in patients with a higher FIGO stage or in those that developed chemoresistance or disease recurrence." (PMID 27081703, 2016). "While all of the tumor cells at both diagnosis and relapse shared the two SNVs in CREBBP and RGS11, five additional mutations in NRF1, MARCKS, USP11, ELK1, and MYC were detected at diagnosis." (PMID 26527318, 2016). "Our results address the role of MARCKS in the tumor stroma as a pivotal regulator of CAF activation." (PMID 27081703, 2016). "Suppression of MARCKS resulted in the loss of CAF features, and diminished role of CAFs in supporting tumor cell growth in 3D organotypic cultures and in murine xenograft model." (PMID 27081703, 2016). "Compared with its expression in the tumor epithelial compartment, MARCKS was noted specifically expressed in the stromal compartment as determined by analysis of EOC-related datasets." (PMID 27081703, 2016). "Conceivably, up-regulation of phospho-MARCKS-dependent production of cytokines, chemokines, and growth factors not only promotes inflammation events but also plays a critical role in tumor proliferation, angiogenesis, and metastasis." (PMID 26015406, 2015). "To further explore the clinical implications of the HER2–MARCKS interaction, we conducted additional RIME profiling using an HR-negative, HER2-positive tumor specimen (Case 3), which confirmed that MARCKS was consistently identified as a HER2 interactor even in the HR-negative context." (PMID 40940979, 2025). "Based on our analysis, we hypothesize that MARCKS plays a pivotal role in promoting the interactions between fibroblasts and tumor cells in the UTUC TME." (PMID 38903524, 2024). "Furthermore, miR-21 has been implicated in promoting the aggressive potential of PC cells by regulating other tumor inhibitors, including the MARCKS protein (Myristoylated Alanine-Rich Protein Kinase C Substrate)." (PMID 37628978, 2023). "A decrease in pMARCKS/MARCKS was observed by C1D15 in patient tumour samples; however, no clear associations were detected between the extent of pMARCKS suppression and LXS196 treatment group." (PMID 36624219, 2023).